ZNF239 (zinc finger protein 239)
Description:
May be involved in transcriptional regulation.
Synonyms: MOK2; HOK-2
Tractability: PROTAC: UniProt records ubiquitination sites on it; ubiquitination databases record sites on it.
Gene: Protein-coding gene on chromosome 10 (43,554,516 to 43,574,623, reverse strand). Ensembl gene ENSG00000196793.
Subcellular location: Nucleus
Subcellular location (Human Protein Atlas): Nuclear bodies; Nucleoplasm
Gene Ontology:
Molecular function: DNA-binding transcription repressor activity, RNA polymerase II-specific; protein binding; RNA polymerase II cis-regulatory region sequence-specific DNA binding; DNA binding; DNA-binding transcription factor activity, RNA polymerase II-specific; RNA binding
Biological process: negative regulation of transcription by RNA polymerase II; regulation of transcription by RNA polymerase II; regulation of gene expression
Cellular component: nuclear body; nucleoplasm; nucleus
Genetic constraint (gnomAD): Loss-of-function variants: 16 observed, 30.16 expected, observed/expected ratio (o/e) 0.53, 90% interval 0.36 to 0.81. The upper end of that interval is the gene's LOEUF score, 0.81, which puts it in group 3 of 6, group 1 being the genes least tolerant of losing a copy. Missense variants: 509 observed, 557.33 expected, observed/expected ratio (o/e) 0.91, 90% interval 0.85 to 0.98. Synonymous variants: 191 observed, 197.55 expected, observed/expected ratio (o/e) 0.97, 90% interval 0.86 to 1.09.
Homologues: Orthologues: macaque ZNF239 (95% identical), dog ZNF239 (73% identical), pig ZNF239 (72% identical), rabbit ZNF239 (64% identical), rat Zfp239 (42% identical), mouse Zfp239 (41% identical). Paralogues in human: ZNF229 (39% identical), ZNF235 (38% identical), ZNF112 (38% identical), ZNF226 (37% identical), ZNF234 (36% identical), ZNF251 (36% identical), ZNF227 (36% identical), ZNF250 (36% identical), ZNF658 (35% identical), ZNF543 (35% identical), ZNF568 (35% identical), ZNF30 (34% identical), and 164 more.
Diseases named in the same sentence as ZNF239 in open-access papers:
ZNF239 is named in the same sentence as 3 diseases in open-access papers, as found by Europe PMC text mining. Sharing a sentence is not in itself a finding about the gene and the disease. The quoted sentences say what the papers report.
hepatocellular carcinoma (1 paper, 2020). A malignant tumor that arises from hepatocytes. "The expression levels of SMG5, EZH2, ZNF239, and IGF2BP3 in different hepatocellular carcinomas were higher than those in the normal group in the Roessler Liver (34868_ at), Roessler Liver (203358_s_at), Roessler Liver (206261_at), and Roessler Liver (203819_s_at) studies." (PMID 33297932, 2020).
liver cancer (1 paper, 2020). An epithelial or non-epithelial malignant neoplasm that arises from the liver. "We analyzed the expression of SMG5, EZH2, FBLL1, ZNF239, and IGF2BP3 in liver cancer using the Oncomine database." (PMID 33297932, 2020).
tumor (3 papers, 2007 to 2020). "The histological level of ZNF239 was not significantly different between tumor and normal tissue." (PMID 33297932, 2020).